HS3ST5 (heparan sulfate-glucosamine 3-sulfotransferase 5)
Description:
Sulfotransferase that utilizes 3'-phospho-5'-adenylyl sulfate (PAPS) to catalyze the transfer of a sulfo group to position 3 of glucosamine residues in heparan. Catalyzes the rate limiting step in the biosynthesis of heparan sulfate (HSact). This modification is a crucial step in the biosynthesis of anticoagulant heparan sulfate as it completes the structure of the antithrombin pentasaccharide binding site. Also generates GlcUA-GlcNS or IdoUA-GlcNS and IdoUA2S-GlcNH2. The substrate-specific O-sulfation generates an enzyme-modified heparan sulfate which acts as a binding receptor to Herpes simplex virus-1 (HSV-1) and permits its entry.
Synonyms: 3-OST-5; 3OST5; HS3OST5; NBLA04021
Tractability: Small molecule: a structure with a bound ligand is known; it has a high-quality binding pocket. Antibody: UniProt predicts a signal peptide or a membrane-spanning region.
Gene: Protein-coding gene on chromosome 6 (114,055,093 to 114,343,209, reverse strand). Ensembl gene ENSG00000249853.
Subcellular location: Golgi apparatus membrane
Pathways (Reactome):
Metabolism: HS-GAG biosynthesis
Gene Ontology:
Molecular function: [heparan sulfate]-glucosamine 3-sulfotransferase activity; protein binding; 3'-phosphoadenosine 5'-phosphosulfate binding; sulfotransferase activity
Biological process: heparan sulfate proteoglycan biosynthetic process; negative regulation of coagulation; regulation of viral entry into host cell
Cellular component: Golgi membrane; membrane
Genetic constraint (gnomAD): Loss-of-function variants: 10 observed, 24.97 expected, observed/expected ratio (o/e) 0.4, 90% interval 0.25 to 0.68. The upper end of that interval is the gene's LOEUF score, 0.68, which puts it in group 2 of 6, group 1 being the genes least tolerant of losing a copy. Missense variants: 324 observed, 437.24 expected, observed/expected ratio (o/e) 0.74, 90% interval 0.68 to 0.81. Synonymous variants: 169 observed, 168.51 expected, observed/expected ratio (o/e) 1, 90% interval 0.88 to 1.14.
Homologues: Orthologues: macaque HS3ST5 (99% identical), rabbit HS3ST5 (98% identical), dog HS3ST5 (98% identical), guinea pig HS3ST5 (97% identical), mouse Hs3st5 (97% identical), pig HS3ST5 (97% identical), rat Hs3st5 (96% identical), tropical clawed frog hs3st5 (91% identical), chimpanzee HS3ST5 (90% identical), Drosophila melanogaster Hs3st-A (49% identical), Caenorhabditis elegans hst-3.1 (36% identical). Paralogues in human: HS3ST1 (44% identical), HS3ST4 (40% identical), HS3ST3A1 (40% identical), HS3ST3B1 (39% identical), HS3ST2 (37% identical), HS3ST6 (35% identical), NDST1 (29% identical), NDST3 (28% identical), NDST4 (28% identical), NDST2 (27% identical).
Diseases named in the same sentence as HS3ST5 in open-access papers:
HS3ST5 is named in the same sentence as 12 diseases in open-access papers, as found by Europe PMC text mining. Sharing a sentence is not in itself a finding about the gene and the disease. The quoted sentences say what the papers report.
autism (3 papers, 2018 to 2022). Persistent deficits in social interaction and communication and interaction as well as a markedly restricted repertoire of activity and interest as well as repetitive patterns of behavior. "Three genes that encode anabolic enzymes, which are among the 107 DEGGs, have been reported as candidate genes for autism, and they are Large1, Galnt9, and Hs3st5." (PMID 36568890, 2022).
metastatic tumors (3 papers, 2015 to 2018). "Regarding the enzymes responsible for the modificaton of the HS chains, alterations were only found in non-metastatic tumors, affecting N-sulfation and the isoforms HS6ST1, HS3ST3B and HS3ST5." (PMID 26482785, 2015). "Interestingly, alterations were found in only non-metastatic tumors, affecting N-sulfation, and the isoforms of heparan sulfate 6-O-sulfotransferase 1 (HS6ST1), heparan sulfate-glucosamine 3-sulfotransferase 3B1 (HS3ST3B1) and heparan sulfate-glucosamine 3-sulfotransferase 5 (HS3ST5)." (PMID 30197623, 2018). "Again the data differ from those obtained in RSCRCs, where none of the isoforms appeared modified in metastatic tumors, and HS3STB1 and HS3ST5 were underexpressed only in non-metastatic ones." (PMID 29940912, 2018).
schizophrenia (2 papers, 2013 to 2018). A major psychotic disorder characterized by abnormalities in the perception or expression of reality. "The association identified in present study suggested evidence that areas of three genes (TBXAS1, PIK3C2G and HS3ST5) or related chromosome regions harbor susceptibility allele for schizophrenia with GM volume as QT." (PMID 24086445, 2013).
Intellectual disability (1 paper, 2024). "The aberrations of the Hs3st5 gene were associated with intellectual disability and microcephaly with pontine and cerebellar hypoplasia." (PMID 39451223, 2024).
adenocarcinoma (1 paper, 2022). A common cancer characterized by the presence of malignant glandular cells. "The top three genes upregulated after castration as compared to adenocarcinomas were the heparan sulfate sulfotransferases HS3ST5 and HS6ST2, and the chondroitin sulfate sulfotransferase CHST11." (PMID 35963852, 2022).
HS3ST5 also shares sentences with these, for which no sentence is quoted: breast carcinoma (1 paper); developmental delay (1); glioblastoma (1); hepatocellular carcinoma (1); invasive breast ductal carcinomas (1); microcephaly (1); pancreatic cancers (1).